PCSK9 (proprotein convertase subtilisin/kexin type 9)
Diseases named in the same sentence as PCSK9 in open-access papers (continued):
Sharing a sentence is not in itself a finding about the gene and the disease.
diabetes (continued). "They compared the effects of lower LDL-C cholesterol levels that were mediated by variants in proprotein convertase subtilisin-kexin type 9 (PCSK9), HMGCR, or both on the risk of cardiovascular events and risk of diabetes in 112,772 participants from 14 studies with use of the MR method." (PMID 32040442, 2020). "The beneficial effect of polydatin in the context of glucose intolerance and diabetes emerged also from in vivo studies: gene and protein expression of PCSK9 was found reduced in the liver and serum of diabetes (db/db) C57BL/6 mice treated with polydatin 100 mg/Kg, 6 d/week for 4 weeks." (PMID 32429343, 2020). "We also apply POINT to the Action to Control Cardiovascular Risk in Diabetes (ACCORD) clinical trial data, finding promising rare variants in PCSK9, ANGPTL4 and CETP that may be associated with lipoprotein-related outcomes." (PMID 30779729, 2019). "Pertinently, they also demonstrated that PCSK9 inhibition did not increase the risk of diabetes or worsen glycemic control." (PMID 31758270, 2019). "Inhibition of PCSK9 in pancreatic cells decreases cholesterol accumulation, which results in glucose metabolism impairment and reduction of insulin secretion, thus favoring diabetes status." (PMID 29562587, 2018). "For primary prevention of CVD in people with diabetes receiving a statin, the absolute benefit of PCSK9 inhibitors is estimated to be around 13–19 people who will avoid major cardiovascular events (per 1000 people treated for 5 years, assuming an annual event rate of 1–1.5%)." (PMID 28025677, 2017). "A recent MR study using genetic variants for proprotein convertase subtilisin-kexin type 9 (PCSK9) and 3-hydroxy-3-methylglutaryl-coenzyme A reductase (HMGCR), that mimic the effects of lowering LDL-C levels, showed an increased risk of diabetes with lower LDL-C." (PMID 28320383, 2017). "Yet, in their study they found lower placental PCSK9 expression levels in the diabetes group." (PMID 27842594, 2016). "However, our study contradicts previous evidence that PCSK9 inhibitors do not increase the risk of diabetes." (PMID 40225015, 2025). "However, this provides reassurance that the risk of diabetes is not directly due to LDL-C lowering or PCSK9 inhibition." (PMID 40648946, 2025). "However, the impact of maternal overweight/obesity and/or diabetes on the concentrations of PCSK9 in the neonatal-placental circulation is unknown." (PMID 38440108, 2024). "Major trials, such as FOURIER and ODYSSEY OUTCOMES, have demonstrated that PCSK9 inhibitors, like evolocumab and alirocumab, provide additional reductions in LDL-C levels and CV risks, particularly benefiting high-risk populations, including those with diabetes and PAD." (PMID 39539858, 2024). "PCSK9 inhibitors did not increase the risk of diabetes or cataracts." (PMID 38988669, 2024). "However, results from large clinical trials suggest that PCSK9 inhibitor treatment does not increase the risk of diabetes." (PMID 39767636, 2024). "In addition, long-term follow-up data on the efficacy or safety of PCSK9 inhibitors are insufficient, and some issues regarding their potential impact on neurocognitive- or diabetes-related risk have not been clearly uncovered." (PMID 36704607, 2023). "Anti-PCSK9 mAb could therefore modify glucose metabolism (through changes of insulin secretion) without necessarily causing diabetes." (PMID 37324254, 2023). "Thus, PCSK9 inhibition has been argued to promote diabetes like statins." (PMID 36527064, 2022).
diabetes (continued). "However, contradictory findings concerning the relationship between dyslipidemia and diabetes are also noted: Hyperlipidemic patients receiving lipid-lowering therapy with PCSK9 inhibitory antibodies or statins show an increased incidence of new-onset diabetes." (PMID 35740449, 2022). "PCSK9 modulators significantly reduce the risk of CV and CV death among patients with CVD (RR = 0.80; 95% CI: 0.73–0.87) and this effect might be even greater in those with pre- and diabetes." (PMID 36443827, 2022). "The study showed that high PCSK9 levels were independently associated with MACEs in STEMI patients with diabetes undergoing primary PCI, and the association may be due to stronger correlations of PCSK9 with inflammation and platelet activation markers in diabetic patients." (PMID 35596184, 2022). "However, restricted by the limited number of participants and the relatively short follow-up period, these clinical trials rule out the long-term effects of PCSK9 mAbs on glycemic parameters and the risk of new-onset diabetes." (PMID 32169071, 2020). "Furthermore, the risk of diabetes, known to be slightly increased under statin therapy in individuals with prediabetes, was increased with a similar magnitude per unit LDL-C reduction for both the PCSK9 and HMGCR polymorphisms." (PMID 33304274, 2020). "Furthermore, we found that PCSK9 was positively associated with ALT, AST, and GGT, liver function indices that are known as sensitive indicators of liver dysfunction and hepatic insulin resistance in diabetes." (PMID 33302966, 2020). "Furthermore, clinical trials showed that PCSK9 inhibitors did not increase the risk of onset-diabetes, whereas genetics studies exhibited a link between PCSK9 genetic variants and risk of type 2 diabetes." (PMID 29618348, 2018). "For example, PCSK9 variants associated with lower LDL-C have also been found to be associated with lower triglyceride and Lp(a) levels, as well as with differences in lipid metabolites and higher levels of HDL-C, fasting glucose, bodyweight, and rates of diabetes." (PMID 29020353, 2018). "Although the data for PCSK9 inhibitors is thus far reassuring, a more subtle effect cannot be excluded and it is notable that widespread acceptance of the link between statins and diabetes came only after large scale meta-analysis including thousands of new cases of diabetes." (PMID 27864787, 2016). "However, PCSK9 inhibitors may be justified in select high-risk patients who are either statin-intolerant or unable to achieve LDL-C targets despite maximal statin therapy, especially those with FH or diabetes." (PMID 40486443, 2025). "Finally, we also bring further evidence to the obesogenic properties of deficiency or KO of the PCSK9 gene, which may lead to other health detriments, notably diabetes, which need to be considered in the context of PCSK9 inhibition medication or future gene editing possibilities." (PMID 39420340, 2024). "In addition, PCSK9 inhibitors have not been proven to be associated with diabetes development." (PMID 37109734, 2023). "Therefore, the use of PCSK9 inhibitors that do not increase the risk of diabetes is recommended." (PMID 36704607, 2023). "Multiple linear regression confirmed PCSK9 E670G as an independent predictor of LDL-C levels, accounting for age, gender, smoking, hypertension, diabetes mellitus, BMI, and lipid-lowering agent use (p = 0.029)." (PMID 37834124, 2023). "This revealed high IP activity in the field of PCSKs, with patents ranging from biomarkers of diabetes (PCSK1 and PCSK2), to biomarkers and drug targets in cancer (FURIN and PCSK6), with the highest number of patents expectedly related to PCSK9." (PMID 36188622, 2022).
diabetes (continued). "Diabetes mellitus (DM): PCSK9 could be positively correlated with the onset of DM, which is characterized by insulin resistance and a relative lack of insulin." (PMID 35806921, 2022). "The authors suggest to measure PCSK9 levels in patients with diabetes to identify the ones with particularly high cardiovascular risk, indicating that these patients might be the ones who might even profit from lower LDL-targets (e.g. < 40 mg/dl) established by therapeutic PCSK9 inhibition." (PMID 33894772, 2021). "Particularly, LVEF, diabetes history, and serum LDL-C, ApoB, glucose, and Pcsk9 levels were significantly different between these subgroups (all P < 0.05)." (PMID 34044829, 2021). "In addition to high-intensity statins, ezetimibe and PCSK9 inhibitors, other medications, including sodium-glucose cotransporter 2 (SGLT-2) inhibitors, have been shown to have both cardiovascular and renoprotective benefits among high-risk patients with diabetes or CKD." (PMID 33648518, 2021). "Serum Pcsk9, LDL-C, Apob, NT-proBnp, CK level, and diabetes history were independent predictors of high SYNTAX scores (P < 0.05)." (PMID 34044829, 2021). "PCSK9 inhibition through the liposomal IFPT vaccine can improve the glucose and insulin tolerance impairments as well as the lipid profile in diabetes." (PMID 34504898, 2021). "ORs with type 2 diabetes mellitus (T2DM) were 1.29 (95% CI 1.11; 1.50) for the GS, as compared to 1.00 (95% CI 0.96; 1.04) for incident T2DM in PCSK9 inhibitor trials." (PMID 31664920, 2019). "Statins remain first-line therapy in patients with diabetes, though newer therapies to reduce LDL-C have emerged, including ezetimibe as an add-on therapy to statins, and injectable PCSK9 inhibitors, both of which are safe and effective in diabetes." (PMID 31758270, 2019). "Thirdly, multi centre clinical trials are indicated to evaluate the synergistic therapeutic effects of targeted combination strategies, such as PCSK9 + CXCL12, with a particular focus on differential treatment outcomes in patients exhibiting metabolic abnormalities, including diabetes and obesity." (PMID 41283645, 2025). "When serum PCSK9 levels were evaluated in the diabetic patients (all in groups 1, 2 and 3, n = 100) compared to the control group 4 (people with no diabetes), these were found to be significantly higher in diabetic patients (p = 0.001), and highest in group 3." (PMID 39623109, 2025). "PCSK9: proprotein convertase subtilisin/kexin type 9, T2DM: type 2 diabetes mellitus." (PMID 40688979, 2025). "Some studies found significantly higher PCSK9 levels in patients with diabetes compared to those without diabetes." (PMID 38757060, 2024). "Regarding the management of lipid abnormalities in diabetes, lowering LDL-C levels is usually the first goal, with the cornerstone of treatment being statins, which may be combined with ezetimibe and/or PCSK9 inhibitors." (PMID 38376536, 2024). "The development of monoclonal antibodies against proprotein convertase subtilisin/kexin type 9 (PCSK9) has enabled additional potent reductions in LDL-C and, consequently, reduction in cardiovascular risk in patients with and without diabetes." (PMID 38612917, 2024). "Although, some Mendelian randomization analyses concomitant with post-marketing monitoring reports evidence of mild increase of hyperglycemia, rather than diabetes, in the first 6 months of the therapy with PCSK9 inhibitors." (PMID 39140033, 2024). "Nonetheless, several studies have reported that PCSK9 LOF variants do not alter fasting blood glucose or insulin levels and are not linked to diabetes development." (PMID 39139638, 2024). "Current approaches to lower plasma lipids in people with and without diabetes mainly include statins and proprotein convertase subtilisin/kexin type 9 (PCSK9) inhibitors, primarily affecting LDL cholesterol." (PMID 37378396, 2023).
diabetes (continued). "However, the need to expand targeted PCSK9 therapy in the future requires an in-depth study of personalized approaches to their use in both CAD and CAD with diabetes." (PMID 38028979, 2023). "Recent studies have shown that Patients who have prodromal diabetes but not yet T2DM lack plasma PCSK9 levels that can forecast their likelihood of developing T2DM." (PMID 36936164, 2023). "Comparison of selected studies (DM2—diabetes mellitus type 2, HMG-CoAR—3-hydroxy-3-methyl-glutaryl-coenzyme-A reductase, PCSK9—proprotein convertase subtilisin/kexin 9, HT—hypertension, PD—Parkinson’s disease, OEA—oleoylethanolamide, PEA—palmitoylethanolamide)." (PMID 37510734, 2023). "In contrast, other drugs that do not act on PCSK9, such as bempedoic acid, do not worsen fasting glucose or HbA1c in patients with diabetes or prediabetes, or increase the incidence of new-onset diabetes in patients with normoglycemia compared with placebo." (PMID 37324254, 2023). "PCSK9 inhibitors do not have an adverse effect on glucose metabolism and the increase in the number of new cases of diabetes." (PMID 36839644, 2023). "The strength of the correlation between plasma PCSK9 and NT-proBNP was likely greater in patients affected by type 2 diabetes mellitus (T2DM) (r = −0.483; p = 0.006) compared to non-diabetic patients (r = −0.235; p = 0.012)." (PMID 36009507, 2022). "A previous report focusing on the kinetics of LDL-C and apoB-100 using stable isotope tracers and their relationship with plasma PCSK9 concentration similarly reported such a disconnection between PCSK9 and LDL-C metabolism in patients with uncontrolled diabetes mellitus." (PMID 35268464, 2022). "Regarding the PCSK9 inhibitors, RCTs have clearly shown that alirocumab or evolocumab administration does not lead to new-onset diabetes or aggravate pre-existent type 2 diabetes mellitus." (PMID 36386319, 2022). "We also did not evaluate the level of PCSK9 and the relationship between circulating PCSK9 and diabetes in the population." (PMID 34380558, 2021). "Also, genetic studies demonstrated that specific PCSK9 variants might increase the risk for the development of diabetes mellitus type 2 (T2D), however this finding could not be evidently verified in randomized controlled trials (RCTs) when PCSK9 inhibitors were exogenously administered." (PMID 33894772, 2021). "To date, no clinical trials have demonstrated an increase rate of diabetes with PCSK9 inhibitor use." (PMID 34869702, 2021). "Both, the FOURIER and the ODYSSEY OUTCOMES trial found a more pronounced absolute risk reduction of a composite of major cardiovascular events in patients with diabetes mellitus receiving PCSK9 inhibitors compared to those without diabetes." (PMID 33894772, 2021). "In this section, we primarily focus on cardiovascular-protective and diabetogenic effects of PCSK9 mAbs in patients with and without diabetes mellitus (DM)." (PMID 32169071, 2020). "Nevertheless, the exact molecular mechanisms by which PCSK9 facilitates the pathogenesis of diabetes are not yet clear." (PMID 33302966, 2020). "Despite statins and/or ezetimibe, many individuals with T2DM or type 1 diabetes mellitus (T1DM) have elevated LDL-C levels and therefore may be candidates for additional LLT with a proprotein convertase subtilisin kexin type 9 (PCSK9) inhibitor." (PMID 31166599, 2019). "Additionally, circulating PCSK9 and VLDL-triacylglycerol concentrations in patients with diabetes have been demonstrated to decrease concomitantly in response to fenofibrate treatment." (PMID 31510106, 2019). "The role of PCSK9 in glycaemic control and diabetes will not be discussed, because the most important findings are already summarized in section “Insulin signaling, diabetes and PCSK9 expression”." (PMID 28439730, 2017). "For now, there is still a lack of clear data about the effect of PCSK9 on pathomechanisms of diabetes." (PMID 29209441, 2017).
diabetes (continued). "Notably, the proportion of HeFH was higher and diabetes mellitus was lower in the high-dose statin pool; also, baseline LDL-C and PCSK9 values were higher in the high-dose statin pool." (PMID 28374849, 2017). "Reductions in atherogenic lipids have been similar in trial participants with and without diabetes in whom circulating PCSK9 levels are also similar." (PMID 28025677, 2017). "Indeed, the link between low PCSK9 levels or its inhibition and LDL-C levels with diabetes suggests a more complex interaction as Mendelian randomization analyses were almost concordant in showing an increased risk of new-onset diabetes in patients treated in the FOURIER and ODYSSEY trials." (PMID 40144869, 2025). "Results were similar for individual ASCVD components, and in sex, race/ethnicity, baseline ASCVD, and diabetes subgroups; however, high impact LDL cholesterol-lowering therapy possibly mitigates the deleterious effect of lipoprotein(a) ≥ 180 nmol/L, most pronounced in those on PCSK9 inhibitors." (PMID 40331569, 2025). "Additionally, a systematic review and meta-analysis of metabolic and cardiovascular outcomes in patients with diabetes confirmed that PCSK9 inhibitors did not affect glucose metabolism." (PMID 39982361, 2025). "For kidney transplant recipients, particularly those with diabetes or chronic allograft nephropathy, PCSK9 inhibitors may not only lower lipids but also reduce proteinuria and preserve graft function." (PMID 41478627, 2025). "Although PCSK9 inhibition therapy may lead to a slight increase in hyperglycemia, this increase is not significant enough to induce new-onset diabetes mellitus." (PMID 39139638, 2024). "In mouse β−cells, PCSK9 deficiency does not influence insulin secretion or the islet content of cholesterol, indicating that PCSK9 inhibition may not exacerbate diabetes." (PMID 39767636, 2024). "Additionally, therapies such as incretins and proprotein convertase subtilisin/kexin type 9 (PCSK9) inhibitors, which support treatments for related conditions, such as diabetes and hypertension, have shown potential in reducing the overall cardiometabolic risk." (PMID 39202647, 2024). "Therefore, anti-PCSK9 vaccination with IFPT vaccine may have antidiabetic effects and improve the lipid profile in diabetes." (PMID 38165521, 2024). "Die Evidenz zu PCSK9-Hemmern auf Basis einer Statintherapie stammt aus der FOURIER Studie (Evolocumab) und deren Subanalysen, in denen sich Patienten mit Diabetes mellitus nicht von denen ohne Diabetes in ihren klinischen Vorteilen durch die Behandlung unterschieden." (PMID 37101037, 2023). "Second, our study lacked healthy individuals or those with pre-diabetes; therefore, we are unsure whether PCSK9 affects diabetes." (PMID 38115042, 2023). "However, mostof the previous studies were designed as direct meta-analyses, and none of themevaluated the relative effects of PCSK9 monoclonal antibodies and bempedoic acidon the secondary prevention of new-onset diabetes and cardiovascular events." (PMID 39077568, 2023). "We aimed to assess the relationship between PCSK9 and major adverse cardiovascular events (MACEs) in ST-segment elevation myocardial infarction (STEMI) patients with or without diabetes, as well as the relationships between PCSK9 and metabolism, inflammation and platelet activation markers." (PMID 35596184, 2022). "Furthermore, the upward trend remained even after adjustment of age, gestational age, BMI, blood pressure, abdominal girth, family history of diabetes mellitus, TG, LDL-C, and HOMA-IR (model 2, model 3, model 4) compared with those in the first quartile of PCSK9 (all P < 0.05 for a linear trend)." (PMID 35498417, 2022). "In our study we describe for the first time, that patients with insufficiently controlled T2D might have a superior LDL-C reduction by PCSK9 inhibitor therapy compared to patients without diabetes mellitus." (PMID 33894772, 2021).